ERBB2 (erb-b2 receptor tyrosine kinase 2)
Diseases named in the same sentence as ERBB2 in open-access papers (continued):
Sharing a sentence is not in itself a finding about the gene and the disease.
breast cancer (continued). "Most of the breast cancers were estrogen receptor positive and/or progesterone receptor positive, and few were ERBB2 positive (eTable 2 in Supplement 1)." (PMID 39745704, 2025). "It has been reported that CPNE3 can induce epithelial–mesenchymal transition (EMT) in breast cancer by activating ErbB2 protein and then can promote the invasion and migration of breast cancer cells." (PMID 41190648, 2025). "In contrast BCL3 drives metastasis in ERBB2-driven mammary tumors, and its expression has been shown to correlate with poor survival in ER + breast cancer, including ILC." (PMID 40597443, 2025). "The detection rate of ERBB2 amplification in our breast cancer cohort was low compared to tissue-based rates, which are approximately 15–20%." (PMID 41590338, 2025). "Separate validations were performed in 3,968 samples for ERBB2 amplification in breast cancer as a complement to the MI Cancer Seek tumor profiling validation, and in 9,213 samples for ALK fusions in NSCLC." (PMID 40804002, 2025). "ERBB2 gene is abnormally highly expressed in various tumor tissues, including breast cancer, ovarian cancer, pancreatic cancer, and others." (PMID 41305721, 2025). "The overall incidence rate of HR-positive and ERBB2-positive breast cancer increased 3.6% per year from 2010 to 2016, but then decreased by 2.9% per year from 2016 to 2019, with a similar pattern observed across different age groups." (PMID 39853979, 2025). "It was approved by the US Food and Drug Administration (FDA) in 2013 for the treatment of advanced human epidermal growth factor receptor 2 (HER2, as known as ErbB2)-positive breast cancer." (PMID 41487530, 2025). "Others, including Cox8a, Ndufb8, and Atad1, which are the genes involved in oxidative phosphorylation pathway, also exhibited an opposite regulation by Srsf3 KO in our Erbb2 breast cancer and DEN-induced liver cancer." (PMID 40568073, 2025). "One of the summits in the breast tumor sample absent from the colon tumor sample corresponds to the bidirectional promoters of MED1 and CDK12, both of which have been shown to functionally cooperate with co-amplified ERBB2 in aggressive breast cancer." (PMID 39946483, 2025). "Breast cancer can be organized into three subtypes based on the gene amplification of epidermal growth factor 2 (ERBB2 or HER2) and the expression of estrogen or progesterone receptors." (PMID 40362524, 2025). "Nonetheless, although these therapies possess a high level of efficacy in ERBB2-positive breast cancer, we observed low overall use as recent as 2020 and a slow increase in uptake over time among all Medicare beneficiaries." (PMID 40310643, 2025). "Breast cancer intrinsic-like subtypes (luminal A–like, luminal B–like, luminal B–ERBB2 [formerly HER2 or HER2/neu]-like, ERBB2 enriched–like, or triple-negative) were determined by immunohistochemistry of tumor sections." (PMID 40622713, 2025). "In breast cancer cells, the mechanism leading to ERBB2 gene overexpression is gene amplification, including copy number." (PMID 40727661, 2025). "We next evaluated the performance of VSV-Gmut-pseudotyped lentiviral vectors preincubated with 929-B6 across three breast cancer cell lines with high ERBB2 expression and one ERBB2-negative control line." (PMID 41472234, 2025). "Specifically, 66 stage III and IV ERBB2 (HER2)-positive breast cancer patients that completed standard therapy were included in the trial." (PMID 40266115, 2025). "For instance, overexpression of HER2 is an important driver of breast cancer, with ERBB2 amplification or overexpression present in approximately 20–30% of breast cancer patients." (PMID 40852352, 2025). "We have also shown that PTPRO can suppress breast cancer progression by affecting the phosphorylation status of ERBB2 and related downstream pathways." (PMID 40016288, 2025).
breast cancer (continued). "HER2-positive breast cancer, characterized by the amplification of the ERBB2 gene, accounts for approximately 15–20% of all breast cancer cases and is associated with aggressive tumor behavior and poor prognosis." (PMID 41234727, 2025). "ErbB-2 is expressed in the same specimens in an increasing proportion of normal breast acini, microcysts, and cancer cells in 36% of specimens with breast cancer." (PMID 41304707, 2025). "Specifically, rates of HR-positive and ERBB2-negative breast cancer are generally increasing, while in more recent years rates of HR-positive and ERBB2-positive and HR-negative and ERBB2-positive cancers are decreasing." (PMID 39853979, 2025). "Overall, incidence rates of HR-negative and ERBB2-positive breast cancer increased 2.9% per year from 2010 to 2015 and then decreased 2.9% per year from 2015 to 2019, with a similar pattern observed across all age groups." (PMID 39853979, 2025). "This study is, to our knowledge, the first to evaluate the association between the HER2DX ERBB2 mRNA score and clinical outcomes in HER2+ advanced breast cancer patients treated with first-line THP chemotherapy." (PMID 40280938, 2025). "We found that STARD7 mRNA levels were comparable in TNBCs, ERα+ and ERBB2+ breast cancer cell lines." (PMID 40443279, 2025). "In comparison to breast cancers in which there was a strong correlation between ERBB2 mRNA and HER2 protein levels (cor = 0.79, p < 0.001), this association was weaker in urothelial cancers (cor = 0.72, p < 0.001)." (PMID 41422272, 2025). "During genetic research, it has been discovered that ErbB2, an RTK protein abnormally increased in HER2-positive breast cancer, interacts with integrin β4." (PMID 40649983, 2025). "Here, we lineage trace millions of transformed cells and thousands of tumors using a cancer rainbow mouse model of HER2 (also known as ERBB2)-positive breast cancer." (PMID 40105775, 2025). "Over 20 years ago, it was reported that humans treated with anti-ERBB2 antibodies for ERBB2-positive breast cancer, and mice with conditional post-natal deletion of Nrg1, Erbb2, or Erbb4 tyrosine kinase receptors, develop cardiomyopathy." (PMID 39794341, 2025). "Among these, T-DXd has shown broad antitumor activity due to its high drug-to-antibody ratio (8:1) and bystander effect, earning FDA approval for HER2-positive and HER2-low breast cancer, ERBB2-mutant NSCLC, and HER2-positive gastric cancers." (PMID 40828885, 2025). "Our study lays a solid foundation for further clinical investigations into the combination of metformin and alpelisib for the treatment of erbB2-overexpressing breast cancer." (PMID 41347072, 2025). "Among 12 765 beneficiaries with ERBB2-positive breast cancer (median [IQR] age, 74 years; 99.2% female), 8.1% were of Black, 6.9% Hispanic, and 85.0% White race and ethnicity, and 54.2% received ERBB2-targeted therapy." (PMID 40310643, 2025). "The high prevalence of ERBB2 amplification in familial breast cancer underscores the importance of genetic screening for first-degree relatives, particularly in high-risk populations." (PMID 41403731, 2025). "This cohort study examines racial and ethnic disparities in the receipt of ERBB2 (formerly HER2 or HER2/neu)–targeted therapies and changes in receipt over time among Medicare beneficiaries with ERBB2-positive breast cancer." (PMID 40310643, 2025). "The ERBB family of receptors, particularly ERBB2 (also known as HER2), has been extensively studied due to its association with aggressive forms of breast cancer and other malignancies." (PMID 40143209, 2025). "In HER2 + breast cancer, BCL-2 expression is negatively correlated with c-erbB2 protein immunostaining and is a marker of poor prognosis." (PMID 40104496, 2025).
breast cancer (continued). "Across breast cancer lines, transduction enhancement correlated with ERBB2 surface density, and co-culture experiments confirmed selective entry into ERBB2+ populations." (PMID 41472234, 2025). "Previously, we demonstrated that metformin, a first-line drug for diabetes, inhibits the proliferation and stemness of erbB2-overexpressing breast cancer cells." (PMID 41347072, 2025). "We previously demonstrated that HDAC5 negatively regulates the expression of the microRNA molecule, miR-125a-5p, and the overexpression of miR-125a-5p decreases the expression of ERBB2 in ER+ breast cancer cells." (PMID 39991577, 2025). "Among 12 765 Medicare beneficiaries diagnosed with ERBB2-positive breast cancer between 2010 and 2019 (median [IQR] age at diagnosis, 74 years; 99.2% female and 0.8% male), 8.1% were of Black, 6.9% Hispanic, and 85.0% White race and ethnicity." (PMID 40310643, 2025). "The irreversible EGFR/ERBB2 inhibitor Neratinib, which is approved for the treatment of ERBB2‐positive breast cancers, emerged as a hit in our drug screening experiment for KRASi‐based combination therapies." (PMID 40956140, 2025). "Outcomes for patients with early ERBB2 (formerly HER2)–positive breast cancer have improved in recent decades because of new effective treatments." (PMID 39946142, 2025). "In contrast, the expression levels of NUPR1 mRNA and ERBB2 protein in the luminal-A subtype-like MCF7 (labelled with a blue colored asterisk in the figure) breast cancer cells are low, as expected." (PMID 39991577, 2025). "Using ErbB2 monoclonal antibodies, typically trastuzumab, to block excess ErbB2 on the cell membrane and inhibit aberrant downstream signaling cascades represents the standard therapeutic option for ErbB2-overexpressing breast cancer patients." (PMID 39786928, 2025). "This study aims to comprehensively elucidate the pathological and molecular significance of ERBB2 (HER2/neu) overexpression in Egyptian familial breast cancer, highlighting its role in tumor aggressiveness, immune evasion, and precision oncology." (PMID 41403731, 2025). "Ganetespib effectively kills resistant cancer cells, including ErbB2-overexpressing breast cancer cells, and it sensitizes other chemotherapeutics in various cancer types." (PMID 41425251, 2025). "Herceptin is an ERBB2-specific monoclonal antibody widely used clinically for treating patients with ERBB2-enriched breast cancer." (PMID 39991577, 2025). "Elevated ERBB2 expressionis associated with breast tumor growth, and suppression ofERBB2 and ERBB3 induces apoptosis in breast cancer cells." (PMID 41541554, 2025). "Our study demonstrates that alpelisib, a PI3K inhibitor, effectively inhibits the proliferation, colony formation, and cancer stemness of erbB2-overexpressing breast cancer cells." (PMID 41347072, 2025). "Cardiac damage and dysfunction have been observed in some patients following anthracycline and trastuzumab treatment of ERBB2 + breast cancer patients." (PMID 39953627, 2025). "The ShortHER randomized clinical trial was a multicentric trial in Italy that enrolled patients with ERBB2-positive breast cancer from December 2007 to October 2013." (PMID 39946142, 2025). "In this cohort study of 12 765 beneficiaries with ERBB2-positive breast cancer, a narrowing of racial and ethnic disparities in receipt of ERBB2-targeted therapies over time was observed." (PMID 40310643, 2025). "ERBB2 is often overexpressed or amplified in various cancers, particularly breast cancer, and enhances tumor aggressiveness and malignancy." (PMID 41439111, 2025). "Kaplan-Meier analysis of expression cohorts of breast tumors showed that high NUPR1 mRNA expression levels correlate with poor overall and relapse-free survival in both endocrine therapy-treated ER+ and ERBB2-enriched breast cancer patients." (PMID 39991577, 2025).
breast cancer (continued). "Here, we performed an extensive time-course analysis of high and low ErbB2-expressing breast cancer cells to describe the regulatory mechanisms of the ErbB2-mediated G1/S transition." (PMID 41161384, 2025). "The ability of MI Cancer Seek to detect ERBB2 (HER2) copy number amplifications (CNAs) in breast cancer was also analyzed." (PMID 40804002, 2025). "In this cohort study of older Medicare beneficiaries with ERBB2-positive breast cancer, we observed a narrowing of racial and ethnic disparities in ERBB2-targeted therapy from 2010-2011 to 2018-2019." (PMID 40310643, 2025). "The abolition of CHD4 in SKBR-3 and BT474 breast cancer cells intervened in the ERBB2 signaling cascade." (PMID 40004553, 2025). "Based on this, we expected that 3oc induced ErbB2 activation and trastuzumab resistance in breast cancer cells via activating the TGF-β signaling pathway." (PMID 39786928, 2025). "Human epidermal growth factor receptor 2 (ERBB2/HER2) is a critical indicator for molecular subtyping and a key therapeutic target in breast cancer." (PMID 40725458, 2025). "ERBB2 encodes human epidermal growth factor receptor 2 (HER2), and is commonly amplified in cancer and is a target of breast cancer therapy." (PMID 39946483, 2025). "Targeted therapies, such as trastuzumab which inhibits this pathway, have demonstrated significant clinical benefit in ERBB2-positive breast cancers." (PMID 40143209, 2025). "It has shown activity in ERBB2-positive breast cancer and is exploring its application in endometrial cancer." (PMID 40046734, 2025). "Although neratinib, a pan-ErbB kinase inhibitor, is approved in ErbB2-positive breast cancer, drug resistance is common." (PMID 39908697, 2025). "Recently, the results of a single-arm phase I clinical trial investigating the ERBB2 plasmid DNA vaccine in breast cancer patients were reported." (PMID 40266115, 2025). "Jaewoo Lim combined FRET with microfluidic technology and signal amplification technology to detect exosomes, achieving a sensitive detection of the breast cancer biomarker ERBB2." (PMID 40699635, 2025). "employed graphene oxide–metal nanocomposites for the diagnosis of breast cancer by detecting epidermal growth factor receptors (ErbB2)." (PMID 40326506, 2025). "Mutations or amplifications in the ERBB2 gene are observed in approximately 5% and 2% of the ER+/HER2− relapsed breast cancer population, respectively, while nearly half of these cases exhibit increased activity of the PI3K/Akt pathway." (PMID 40244377, 2025). "In this cohort study of older Medicare beneficiaries diagnosed with ERBB2-positive breast cancer between 2010 and 2019, we observed a narrowing of racial and ethnic disparities in the receipt of ERBB2-targeted therapies over time." (PMID 40310643, 2025). "In mammary carcinoma cells, decorin also interacts with ErbB4 and indirectly reduces ErbB2 levels, likely by decreasing ErbB2/ErbB4 heterodimers." (PMID 40136510, 2025). "Numerous studies have elucidated the role of AKT3 as a driver of endocrine therapy and AKT inhibitor resistance in ErbB2-driven breast cancer and breast cancer in general." (PMID 39614261, 2024). "Our study focused on the regulatory role of miR‐449c‐5p in breast cancer and its targeting relationship with ERBB2." (PMID 38351535, 2024). "ER+ErbB2- breast cancers have a relatively low response to chemotherapy with an approximate pCR rate of 5%-15%, indicating a variable spectrum of tumor biology and chemotherapy responsiveness." (PMID 39006626, 2024). "Overall, 2 patients experienced partial response, 1 with EGFR-amplified glioblastoma and 1 with multiple brain metastases from ERBB2-amplified and ERBB3-mutated breast cancer." (PMID 38680990, 2024). "This study investigates the potential of drug combinations to enhance therapeutic strategies in HER2-positive breast cancer by targeting the ERBB2 signaling pathway." (PMID 39684551, 2024).
breast cancer (continued). "ErbB2, alternatively referred to as HER2, represents a transmembrane glycoprotein belonging to the ErbB family of proteins, distinctly acknowledged as an oncogene commonly overexpressed in breast cancer." (PMID 39668367, 2024). "In this study, we systematically re-assessed HER2 copy number, HER2/CEP17 ratio and ERBB2 mRNA in a trastuzumab-treated breast cancer cohort and investigated the biomarkers in a continuous manner in relation to RFS." (PMID 38321542, 2024). "Here, we investigate the role of Carnitine palmitoyl transferase 1a (Cpt1a), a key enzyme in long-chain fatty acid (LCFA) oxidation, in ErbB2-driven breast cancers." (PMID 39097623, 2024). "For example, ERBB2 (HER2) amplification, which is observed in 15–20% of breast cancers, significantly impacts patient response to trastuzumab-based treatments." (PMID 39596466, 2024). "The receptor tyrosine kinase (RTK) HER2 (ErbB-2), a major target for breast cancer therapy, is overexpressed in about 25% of breast cancer cases." (PMID 38540084, 2024). "Although traditionally it has been known for its assignment with breast cancer, ERBB2 overexpression, usually due to in-frame insertions and amplifications, has been identified in CRC and NSCLC alike." (PMID 38920700, 2024). "ERBB2 gene amplification and HER2 overexpression are found in 20% of breast cancers, correlating with more aggressive forms of the disease." (PMID 39684551, 2024). "The other type is EVPs closely related to cell specificity, such as tetraspanins (e.g., CD37 and CD53 in leukocytes), ERBB2 in breast cancer, CD45 in immune cells, and major histocompatibility complex class (MHC) and II." (PMID 38814362, 2024). "The KEYNOTE-756 trial (NCT03725059) completed accrual and is currently investigating the addition of pembrolizumab to NAT and adjuvant endocrine therapy in high-grade (3/3) ER+ErbB2- breast cancer patients." (PMID 39006626, 2024). "MDA-MB-231 exhibits significantly higher ERBB family member expression compared to KRAS wildtype MDA-MB-436 cells and seems to belong to the HER2/ERBB2 low breast cancer category." (PMID 38896334, 2024). "Deeper insights into ERBB2-driven cancers are essential to develop new treatment approaches for ERBB2+ breast cancers (BCs)." (PMID 39067134, 2024). "Protein MAL2 mediates lipid raft formation, leading to ErbB2 plasma membrane retention and enhanced ErbB2 signaling in breast cancer cells." (PMID 39329960, 2024). "In Rarb−/− mice (RARβ-null mice), ErbB2-induced mammary tumors display a decrease in the proliferation of neoplastic cells, as well as a diminution of the angiogenetic process, the levels of collagen and the recruitment of inflammatory cells." (PMID 38360674, 2024). "Breast cancer can be categorized into molecular subtypes according to gene expression patterns, including luminal-like, ErbB2+ (human epidermal growth factor receptor 2 (HER2)-enriched), and basal-like." (PMID 38338729, 2024). "We employed the Collaborative Cross (CC) mouse model to unearth genetic factors underpinning Erbb2-driven mammary tumour development and metastasis." (PMID 39067134, 2024). "The data reported for ErbB2-induced mammary tumors were confirmed also in the case of Wnt1-induced mammary tumorigenesis." (PMID 38360674, 2024). "Clinically relevant amplification drivers such as ERBB2 in breast cancers (FF: 7.7%, FFPE:4.7%), GNAS (20q13) in colorectal cancers (FF: 6.4%, FFPE: 4.5%), and CCND1 (FF: 6.9%, FFPE: 8.5%) were comparably retrieved." (PMID 39231944, 2024). "HER2-enriched breast cancer is characterized by the amplification of the HER2/ERBB2 oncogene and responds to targeted anti-HER2 therapy." (PMID 38919805, 2024).